GLCE (glucuronic acid epimerase)
Description:
Converts D-glucuronic acid residues adjacent to N-sulfate sugar residues to L-iduronic acid residues, both in maturing heparan sulfate (HS) and heparin chains. This is important for further modifications that determine the specificity of interactions between these glycosaminoglycans and proteins.
Synonyms: Hsepi; KIAA0836
Tractability: Small molecule: a structure with a bound ligand is known. Antibody: UniProt predicts a signal peptide or a membrane-spanning region. PROTAC: ubiquitination databases record sites on it; its protein half-life has been measured.
Gene: Protein-coding gene on chromosome 15 (69,160,584 to 69,272,217, forward strand). Ensembl gene ENSG00000138604.
Subcellular location: Golgi apparatus membrane
Subcellular location (Human Protein Atlas): Mitochondria
Pathways (Reactome):
Metabolism: HS-GAG biosynthesis
Gene Ontology:
Molecular function: calcium ion binding; heparosan-N-sulfate-glucuronate 5-epimerase activity; protein homodimerization activity; racemase and epimerase activity, acting on carbohydrates and derivatives
Biological process: heparan sulfate proteoglycan biosynthetic process; heparin proteoglycan biosynthetic process; negative regulation of cell projection organization; positive regulation of cell population proliferation; positive regulation of SMAD protein signal transduction
Cellular component: Golgi apparatus; Golgi membrane
Genetic constraint (gnomAD): Loss-of-function variants: 14 observed, 42.46 expected, observed/expected ratio (o/e) 0.33, 90% interval 0.22 to 0.51. The upper end of that interval is the gene's LOEUF score, 0.51, which puts it in group 2 of 6, group 1 being the genes least tolerant of losing a copy. Missense variants: 501 observed, 722.54 expected, observed/expected ratio (o/e) 0.69, 90% interval 0.64 to 0.75. Synonymous variants: 217 observed, 256.19 expected, observed/expected ratio (o/e) 0.85, 90% interval 0.76 to 0.95.
Homologues: Orthologues: chimpanzee GLCE (99% identical), macaque GLCE (99% identical), dog GLCE (97% identical), pig GLCE (96% identical), rat Glce (96% identical), mouse Glce (96% identical), rabbit GLCE (96% identical), guinea pig GLCE (95% identical), tropical clawed frog glce (76% identical), zebrafish glceb (73% identical), zebrafish glcea (68% identical), Drosophila melanogaster Hsepi (41% identical), and 1 more.
Diseases named in the same sentence as GLCE in open-access papers:
GLCE is named in the same sentence as 27 diseases in open-access papers, as found by Europe PMC text mining. Sharing a sentence is not in itself a finding about the gene and the disease. The quoted sentences say what the papers report.
breast carcinoma (9 papers, 2010 to 2024). "The involvement of TCF4/β-catenin in regulating GLCE expression was shown also for MCF7 breast cancer cells both in vitro and in vivo." (PMID 39318629, 2024). "The results differ from those for benign and malignant breast tumors, where 36% and 82–84% of the tested samples revealed significantly decreased GLCE expression 10, suggesting a possible tissue specificity of GLCE regulation." (PMID 24403231, 2013). "In this study, an effect of GLCE ectopic expression on cell proliferation and viability of breast carcinoma cells MCF7 in vitro and its potential molecular mechanisms were investigated." (PMID 20723247, 2010). "As a first step of the study, GLCE expression in human breast cancer cells MCF7 was estimated using multiplex RT-PCR." (PMID 20723247, 2010). "In recent years, GLCE has been identified as one of the key enzymes involved in the biosynthesis of acetyl heparin sulfate, which plays a tumour-suppressive role in the pathogenesis of breast cancer." (PMID 34233293, 2021). "We hypothesized that GLCE expression could be involved in regulation of breast cancer cell proliferation through the changed structure/composition of cell surface heparan sulfates and tumour microenvironment." (PMID 20723247, 2010). "Interestingly, all those changes have a clearly anti-metastatic trend - re-expression of GLCE in breast cancer cells MCF7 up-regulates the expression of suppressor genes SYK and NME1 and down-regulates the expression of metastasis marker S1004A and TGFβ." (PMID 20723247, 2010). "In addition, GLCE suppresses the proliferation of human breast cancer cells." (PMID 39337548, 2024). "It was found that the down-regulation of GLCE may indeed lead to breast cancer." (PMID 27112211, 2016). "To test this hypothesis, we ectopically expressed D-glucuronyl C5-epimerase in MCF7 breast cancer cells at the physiological level and analyzed a proliferative activity and viability of the epimerase-expressing cells as well as possible molecular mechanisms of the functional effect of GLCE in vitro." (PMID 20723247, 2010). "In breast cancer cells, epigenetic regulation of GLCE is thought to be dependent on chromatin structure and not DNA methylation as GLCE expression was significantly increased following histone deacetylase (HDAC) inhibitor treatment, but was unaffected by 5-Aza-dc treatment." (PMID 28672878, 2017). "In contrast to breast cancer (where almost no GLCE upregulation was observed), prostate pathological tissues were characterized by a predominant increase in GLCE expression in 49% of the BPH tissues and a decrease in GLCE expression in 53% of the prostate tumor tissues." (PMID 24403231, 2013). "GLCE is another a multiregulated gene, where GLCE expression in breast cancer is controlled through complex molecular mechanisms, including at least chromatin structure, TCF4/b-catenin complex, and microRNA-218, but not GLCE promoter methylation 14–17." (PMID 24403231, 2013).
prostate carcinoma (5 papers, 2013 to 2024). A carcinoma that arises from epithelial cells of the prostate gland. "In breast and lung cancers, GLCE has a demonstrated anti-proliferative effect, but its overexpression in prostate cancer cells is associated with a much more aggressive phenotype." (PMID 28672878, 2017). "The balanced activation of HS-biosynthetic machinery in prostate cancer cells upon the ectopic over-expression of GLCE was evidently more profound than an influence of chemical drugs or presence of other cell types alongside." (PMID 24782989, 2014). "According to the obtained results, normal prostate, BPH, and prostate cancer differ in terms of GLCE expression, which was decreased in 10% of the BPH samples and 53% of the tumor samples." (PMID 24403231, 2013). "The examined prostate carcinoma cell lines showed GLCE mRNA levels 2- to 3-fold lower than the PNT2 normal prostate epithelial cells, whereas, 1.5- to 2.5-fold differences in GLCE expression were also observed between the cell lines." (PMID 24403231, 2013). "GLCE was ubiquitously expressed in normal prostate epithelial cells, while BPH or prostate cancer epithelial cells showed a high heterogeneity in terms of GLCE expression levels." (PMID 24403231, 2013). "In this study, GLCE expression in prostate tumors and prostate cancer cell lines and its epigenetic regulation by GLCE promoter hypermethylation were examined." (PMID 24403231, 2013). "Conversely, in prostate cancer cells, GLCE dysregulation appears to be largely mediated via aberrant GLCE promoter methylation, which varies dramatically between prostate cancer cell types and has been proposed to be a potential contributor to intratumor heterogeneity." (PMID 28672878, 2017). "However, in prostate tissues, GLCE promoter methylation occurs in certain morphological subtypes of prostate cancer epithelial cells and contributes to the overall inactivation of the gene in the cells." (PMID 24403231, 2013). "In conclusion, the obtained results show high intratumor heterogeneity of GLCE expression in prostate cancer cells in vivo and cell lines in vitro, which could be determined by the different extent of GLCE promoter methylation in the cancer cell population." (PMID 24403231, 2013). "d-glucuronyl C5-epimerase (GLCE) was shown as a potential tumor suppressor gene which participated in lung and breast carcinogenesis by inhibiting tumor angiogenesis and invasion/metastasis pathways, which was also proved to affect angiogenesis in prostate cancer cells." (PMID 32489319, 2020). "Thus, at least four known “players” could contribute to the regulation of GLCE expression, and the balance between them will determine the GLCE expression level in every single prostate cancer cell and serve as a foundation for the high heterogeneity of the cells inside a tumor." (PMID 24403231, 2013). "The obtained results reveal the complex deregulation of GLCE expression in prostatic diseases compared with normal prostate tissue and suggest that GLCE may be used as a potential model to study the functional role of intratumor cell heterogeneity in prostate cancer progression." (PMID 24403231, 2013). "The obtained results on the complex deregulation of GLCE expression and promoter methylation in prostate pathology suggest that GLCE may be a gene of interest in the study of the functional role of intratumor cell heterogeneity in prostate cancer progression and treatment." (PMID 24403231, 2013). "A tumor suppressor function has been demonstrated for GLCE in breast and lung carcinogenesis; however, no data are available as to the expression and regulation of the gene in prostate cancer." (PMID 24403231, 2013). "This study reveals the complex deregulation of d-glucuronyl C5-epimerase (GLCE) expression in benign prostatic hyperplasia and prostate tumours, and the high intratumour heterogeneity of prostate cancer cells in terms of GLCE expression and promoter methylation." (PMID 24403231, 2013).
prostate tumors (3 papers, 2013 to 2021). "However, the increased expression of GLCE is associated with advanced pathophysiology of prostate tumors, which indicates that the role of GLCE in different cancers is diverse." (PMID 34122521, 2021). "An antiproliferative effect of D-glucuronyl C5-epimerase (GLCE) has been ascertained in breast and small lung cancer cells, whereas increased GLCE expression has been associated with advanced stages of prostate tumors." (PMID 32916872, 2020). "According to our research, the upregulation of GLCE is related to the poor prognosis of ES, which suggests that the mechanism of action of this gene in ES is similar to that observed in prostate tumors." (PMID 34122521, 2021). "In this study, decreased GLCE expression was observed in 10% of benign prostate hyperplasia (BPH) tissues and 53% of prostate tumors, and increased GLCE mRNA levels were detected in 49% of BPH tissues and 21% of tumors." (PMID 24403231, 2013). "However, a significant decrease in GLCE expression was observed in 53% of the prostate tumors compared with the GLCE expression level in normal prostate tissue, and another 47% expressed GLCE at the normal or elevated levels." (PMID 24403231, 2013). "Of note, MSP analysis and bisulfite sequencing of the GLCE promoter region in prostate tumors revealed no GLCE promoter methylation in vivo." (PMID 24403231, 2013). "Methyl-specific polymerase chain reaction (PCR), bisulfite sequencing, and deoxy-azacytidin (aza-dC) treatment identified differential GLCE promoter methylation (LNCaP 70–72%, PC3 32–35%, DU145, and PNT2 no methylation), which seems to contribute to heterogeneous GLCE expression in prostate tumors." (PMID 24403231, 2013).
breast tumors (2 papers, 2010 to 2013). "Our previous data on significant down-regulation of GLCE expression in human breast tumours suggested a possible involvement of the gene in carcinogenesis." (PMID 20723247, 2010). "Down-regulation of GLCE expression in human breast tumours suggests a possible involvement of the gene in carcinogenesis." (PMID 20723247, 2010). "GLCE expression is significantly decreased in breast tumors 10 and lung cancer cell lines 11, and its restoration suppresses cancer cell proliferation in vitro and tumor growth in vivo, suggesting a tumor suppressor function for GLCE in breast and small-cell lung cancers 11,12." (PMID 24403231, 2013).
colon carcinoma (2 papers, 2024). "β-catenin enhances the D-Glucuronyl C5-epimerase (GLCE) enzymatic activity in human colon carcinoma cell lines." (PMID 39337548, 2024).
lung carcinoma (2 papers, 2013 to 2021). "As a potential tumor suppressor gene, GLCE participates in the occurrence and development of breast and lung cancer, mainly through the inhibition of tumor angiogenesis and invasion/metastasis pathways." (PMID 34122521, 2021). "Recently, a direct involvement of GLCE in carcinogenesis was shown for breast and lung cancer." (PMID 24403231, 2013). "However, in spite of the similar antiproliferative action of GLCE in the examined tissues, its molecular mechanisms in breast and lung cancers differ." (PMID 24403231, 2013).
endometrial cancer (1 paper, 2021). Primary or metastatic malignant neoplasm involving the endometrium (mucous membrane that lines the endometrial cavity). "Therefore, in summary, the MONC/miR-636/GLCE axis may play an important role in human endometrial cancer, and put forward a promising treatment target for endometrial cancer." (PMID 34193130, 2021).
Ewing sarcoma (1 paper, 2021). A small round cell tumor that lacks morphologic, immunohistochemical, and electron microscopic evidence of neuroectodermal differentiation. "As shown in Figure 13A1–13B2, GLCE expression was higher in immunohistochemically stained regions in Ewing's sarcoma than in paraneoplastic tissue." (PMID 34233293, 2021). "In this study, we also observed that the glycolysis-related genes GLCE and TPI1 can be used to construct a prognostic model of Ewing's sarcoma and that their high-risk group corresponds to a significantly poor survival status." (PMID 34233293, 2021). "The GLCE expression was significantly higher in Ewing's sarcoma than in paraneoplastic tissues, whereas the TPI1 expression was significantly higher in paraneoplastic tissues than in Ewing's sarcoma, which is consistent with our bioinformatics analysis results." (PMID 34233293, 2021).
frontotemporal lobar degeneration (1 paper, 2020). "Additionally, GLCE expression was significantly decreased in the brains of patients with frontotemporal lobar degeneration with TDP-43 inclusions (FTD-TDP) relative to normal controls." (PMID 33106318, 2020).
metastatic tumors (1 paper, 2018). "An overexpression in the transcription levels of the two genes involved, GLCE and HS2ST1, was detected in non-metastatic LSCRCs in this study, although not in metastatic tumors, in contrast to our previous study in RSCRCs which found no alterations in the expression of these genes." (PMID 29940912, 2018).
Obesity (1 paper, 2025). Accumulation of substantial excess body fat. "In addition, GLCE deficiency in the liver promotes obesity, and reduced GLCE expression further reduces hepatic secretion of GDF15, which in turn interferes with lipid metabolism and energy homeostasis." (PMID 41497483, 2025).
omphalocele (1 paper, 2018). Omphalocele is an embryopathy classified in the group of abdominal celosomias and is characterized by a large hernia of the abdominal wall, centered on the umbilical cord, in which the protruding viscera are protected by a sac. "Further study of the function of GLCE and other genes might lead to a better understanding of the molecular mechanism of omphalocele." (PMID 30538881, 2018).
osteosarcoma (1 paper, 2022). A usually aggressive malignant bone-forming mesenchymal neoplasm, predominantly affecting adolescents and young adults. "We developed a new prognostic risk model for osteosarcoma based on 7 glycolytic genes (INSR, FAM162A, GLCE, ADH5, G6PD, SDC3, HS2ST1) by bioinformatics." (PMID 36387908, 2022). "A risk model based on seven glycolytic genes (INSR, FAM162A, GLCE, ADH5, G6PD, SDC3, HS2ST1) can effectively evaluate the prognosis of osteosarcoma, and in vitro experiments also confirmed the important role of INSR in promoting OS migration." (PMID 36387908, 2022).
prostate adenocarcinoma (1 paper, 2013). "GLCE expression was determined in normal human prostate epithelial cells (PNT2) and hormone-dependent (LNCaP) or hormone-independent (PC3, DU145) prostate adenocarcinoma cells using multiplex and real-time RT-PCR analyses." (PMID 24403231, 2013).
renal fibrosis (1 paper, 2025). A final common manifestation of a wide variety of chronic kidney diseases characterized by glomerulosclerosis and tubulointerstitial fibrosis. "Its mechanisms may involve promoting renal fibrosis through oxidative stress and inflammatory pathways and further aggravating DN progression by influencing PM‐RGs such as KAZALD1, GLCE, and RPRD1B." (PMID 41497483, 2025).
Spherocytosis (1 paper, 2021). The presence of erythrocytes that are sphere-shaped. "Glucuronic acid epimerase (GLCE), is primarily associated with spherocytosis." (PMID 34233293, 2021).
tumor (11 papers, 2010 to 2025). "GLCE is an enzyme in the heparan sulfate/heparin synthesis that regulates inflammatory response and tumor metastasis." (PMID 39337548, 2024). "Further explorations into the regulatory mechanism of MONC, revealed low expression of GLCE, a tumor suppressor gene, in EC and that GLCE mRNA is the target of miR-636." (PMID 34193130, 2021). "Then we detected the expression of GLCE in the tumor using western blot." (PMID 34193130, 2021). "Several other genes in our model have been independently verified as oncogenes (SPAG5, PARM1) or tumor suppressors (VEPH1, GLCE) in prostate or other cancers, showcasing the ability of our TET2-based model to capture these key changes." (PMID 33008340, 2020). "Likewise, SMARCA2, GLCE, and EFEMP1 showed tumor-suppressor and anti-proliferative activities." (PMID 32610656, 2020).
cancer (8 papers, 2010 to 2021). A tumor composed of atypical neoplastic, often pleomorphic cells that invade other tissues. "Altered expression of GLCE, the epimerase controlling HS GlcA/IdoA ratio, was also reported in cancer." (PMID 34858858, 2021). "A study conducted in 2011 on GLCE in cancer reported that the ectopic re-expression of GLCE exerts an antitumour effect and hence, it is a potential cancer suppressor gene." (PMID 34233293, 2021). "Furthermore, anti-proliferative effects were reported on both breast and small-cell lung cancer cells after induced re-expression of GLCE, highlighting this gene as a potential tumour-suppressor gene." (PMID 34858858, 2021). "Transcriptional patterns of HS-metabolic enzymes (EXT1, EXT2, NDST1, NDST2, GLCE, 3OST1/HS3ST1, SULF1, SULF2, HPSE) were determined in normal, benign, and cancer human prostate tissues and cell lines (PNT2, LNCaP, PC3, DU145)." (PMID 24782989, 2014). "The dysregulation of GLCE expression has been observed in many cancer types, but its exact role in cancer progression is not clear." (PMID 28672878, 2017).
infection (1 paper, 2020). The state of being infected such as from the introduction of a foreign agent such as serum, vaccine, antigenic substance or organism. "Then, viral loads in JEV-infected SLC35B2, HS6ST1, B3GAT3, and GLCE KO cells and in WT PK-15 cells were measured at 18 hpi (hours post-infection) by plaque assay, which only using JEV at an MOI of 0.03 or 0.1." (PMID 33057066, 2020).
GLCE also shares sentences with these, for which no sentence is quoted: anaplastic astrocytoma (1 paper); astrocytoma (1); benign prostatic hyperplasia (1); glioblastoma (1); glioma (1); Hypertension (1); mouth ulcers (1); small cell lung carcinoma (1).